CNPPD1 (cyclin Pas1/PHO80 domain containing 1)
Synonyms: C2orf24; CGI-57
Tractability: Antibody: UniProt predicts a signal peptide or a membrane-spanning region. PROTAC: ubiquitination databases record sites on it.
Gene: Protein-coding gene on chromosome 2 (219,170,704 to 219,182,664, reverse strand). Ensembl gene ENSG00000115649.
Subcellular location: Membrane
Gene Ontology:
Molecular function: cyclin-dependent protein serine/threonine kinase regulator activity; protein kinase binding
Cellular component: cyclin-dependent protein kinase holoenzyme complex; nucleus; membrane
Genetic constraint (gnomAD): Loss-of-function variants: 37 observed, 46.86 expected, observed/expected ratio (o/e) 0.79, 90% interval 0.61 to 1.04. The upper end of that interval is the gene's LOEUF score, 1.04, which puts it in group 4 of 6, group 1 being the genes least tolerant of losing a copy. Missense variants: 503 observed, 519.6 expected, observed/expected ratio (o/e) 0.97, 90% interval 0.9 to 1.04. Synonymous variants: 207 observed, 214.23 expected, observed/expected ratio (o/e) 0.97, 90% interval 0.86 to 1.08.
Homologues: Orthologues: chimpanzee CNPPD1 (98% identical), macaque CNPPD1 (96% identical), dog CNPPD1 (91% identical), pig CNPPD1 (90% identical), guinea pig CNPPD1 (89% identical), mouse Cnppd1 (85% identical), rat Cnppd1 (84% identical), tropical clawed frog cnppd1 (49% identical), zebrafish cnppd1 (45% identical), Drosophila melanogaster CG40191 (20% identical), Caenorhabditis elegans F09G2.2 (16% identical).
Diseases named in the same sentence as CNPPD1 in open-access papers:
CNPPD1 is named in the same sentence as 2 diseases in open-access papers, as found by Europe PMC text mining. Sharing a sentence is not in itself a finding about the gene and the disease.
CNPPD1 shares sentences with these, for which no sentence is quoted: renal cell carcinoma (1 paper); tumor (1).